CRP (C-reactive protein)
Diseases named in the same sentence as CRP in open-access papers (continued):
Sharing a sentence is not in itself a finding about the gene and the disease.
Insulin resistance (continued). "Furthermore, the observational period of three months might have been too short to observe certain changes in metabolic status as e.g. development of insulin resistance or the processes leading eventually to increased CRP." (PMID 22044502, 2011). "Indeed, several studies showed that the association of CRP with insulin resistance was independent of obesity." (PMID 22114593, 2011). "The aim of our study was to investigate whether insulin resistance is associated with CRP independent of abdominal obesity in the Chinese patients diagnosed with type 2 diabetes." (PMID 21167068, 2010). "There is debate as to whether the association between C-reactive protein (CRP) and insulin resistance is independent of body fatness, particularly central obesity." (PMID 21167068, 2010). "There is debate as to whether the association between CRP and insulin resistance is independent of body fatness, particularly central obesity." (PMID 21167068, 2010). "Finally, we did not have the data concerning central obesity, insulin resistance, and minor and new cardiovascular risk factors including albuminuria, homocystinemia, C-reactive protein (CRP), and adiponectin." (PMID 16842631, 2006). "The C-reactive protein-triglyceride glucose index (CTI), a novel composite marker reflecting inflammation and insulin resistance (IR), has shown prognostic value in cardio-cerebrovascular diseases." (PMID 42257031, 2026). "At baseline, participants exhibited elevated glucose, insulin, homeostatic model assessment for insulin resistance (HOMA-IR), triglycerides, and C-reactive protein (CRP) levels, consistent with insulin resistance and chronic low-grade inflammation." (PMID 41683970, 2026). "The C-reactive protein–triglyceride–glucose index (CTI) has emerged as a novel metric for evaluating the severity of inflammation and the degree of insulin resistance." (PMID 40988175, 2025). "Primary outcomes included insulin resistance (HOMA-IR), insulin sensitivity (Matsuda index), mtDNA DAMPs (ND1, ND6), pro/anti-inflammatory cytokines (IFN-γ, IL-10, IL-6, IL-8, TNF-α), CRP, and cortisol." (PMID 41156500, 2025). "Recently, the C-reactive protein–TyG index (CTI), which integrates insulin resistance and systemic inflammation, has been identified as a valuable predictor of cardiovascular disease, stroke risk, and liver fibrosis progression." (PMID 41115075, 2025). "Biomarkers such as CRP, IL-6, and TNF-α serve as indicators of inflammation, while HOMA-IR, fasting insulin, and HbA1c are essential for evaluating insulin resistance." (PMID 40002771, 2025). "While our experiments focused on two widely used platelet agonists (CRP-XL and SFLLRN), further experiments with other agonists such as oxLDL that have close relevance to individuals with insulin resistance would be another interesting aspect of future work." (PMID 40304758, 2025). "This study revealed that the TyG index had a good correlation with indices reflecting insulin resistance, such as BMI, WC, HOMA-IR score, WBC count, and fasting insulin, as well as FPG, HbA1c, HDL-C, TG, ferritin, and CRP levels." (PMID 40507147, 2025). "A recent meta-analysis further confirmed significantly elevated circulating LPS levels in both simple steatosis and MASH patients, which correlated with histological severity, serum C-reactive protein (CRP), and markers of insulin resistance." (PMID 40438102, 2025). "The C-reactive protein-triglyceride glucose index (CTI) is emerging as a novel indicator for comprehensively assessing the severity of both inflammation and insulin resistance." (PMID 38965367, 2025). "According to some authors, plasma high-sensitivity C-reactive protein level (hs-CRP) > 2 mg/L and homeostasis model assessment (HOMA) with insulin resistance score ≥ 2.5 should also be considered as separate metabolic criteria for MASLD." (PMID 40863135, 2025).
Insulin resistance (continued). "IMAT was measured via calf muscle MRI, and body composition (BMI, fat mass index), metabolic markers (hs‐CRP, TNF‐α, IL‐6, insulin resistance), and circulating cell‐free mitochondrial DNA (ccf‐mtDNA) were assessed." (PMID 40635410, 2025). "These benefits are reflected in lower C-reactive protein (CRP) levels and improvements in the triglyceride-to-HDL (TG/HDL) ratio, a key marker of insulin resistance." (PMID 40892247, 2025). "↓ Blood glucose, ↓ homeostatic model assessment of insulin resistance (HOMA-IR), ↓ glycated hemoglobin, ↓ serum MDA and high-sensitivity C-reactive protein (hs-CRP) levels." (PMID 40722870, 2025). "For the obese cohort, age was matched, but PCOS subjects had a greater BMI and showed increased insulin resistance, hyperandrogenemia with an elevated testosterone and FAI and increased CRP (a marker of inflammation)." (PMID 41226313, 2025). "Lastly, the study lacked data on crucial inflammatory and metabolic biomarkers such as C- reactive protein (CRP), insulin resistance indicators, or lipid profiles." (PMID 40600577, 2025). "The HAMD/HAMA/FF scores showed significant correlations with several factors such as PGE, CRP, GAL, GALR1, insulin resistance, and PAI1 levels." (PMID 40048451, 2025). "Research has revealed that the C-reactive protein-triglyceride glucose index (CTI) reliably indicates the presence of inflammation and insulin resistance." (PMID 40988273, 2025). "Vitamin E has preventive and protective effects on MASLD by improving hepatic steatosis (FLI, L/S ratio), insulin resistance (HOMA-IR), oxidative stress (MDA), inflammation (hs-CRP, TNF-α, IL-6, leptin, adiponectin), and hepatocyte apoptosis (CK18-M30)." (PMID 40668532, 2025). "Systemic inflammation in COPD contributes to insulin resistance by increasing pro-inflammatory cytokines (TNF-α, IL-6, and CRP), which impair glucose metabolism and beta-cell function." (PMID 40142617, 2025). "Immune-metabolic markers included body mass index (BMI), fasting glucose (FG), fasting insulin, Homeostasis Model Assessment-Insulin Resistance (HOMA2-IR), C reactive protein and blood lipids." (PMID 41005771, 2025). "BMI, body mass index; HDL, high-density lipoprotein; LDL, low-density lipoprotein; HOMA-IR, homeostatic model for the assessment of insulin resistance; CRP, C-reactive protein." (PMID 40108677, 2025). "Fasting blood sugar (FBS), insulin resistance (IR), total antioxidant capacity (TAC), malondialdehyde (MDA), C-reactive protein (CRP), tumor necrosis factor-alpha (TNF-α), and AMH were measured before and after the study." (PMID 38778429, 2024). "Effects on fasting glucose and insulin, Homeostatic Model Assessment of Insulin Resistance (HOMA-IR), HbA1c, adiponectin, leptin, IL-6, TNF-α, and C-reactive protein (CRP) in exercise vs control groups were analyzed using random effects meta-analysis." (PMID 38253590, 2024). "Insulin sensitivity was assessed using a Homeostatic Model Assessment of Insulin Resistance (HOMA-IR) and C-reactive protein (CRP) levels were used as a proxy for inflammation." (PMID 38337673, 2024). "The increased production of C-Reactive Protein (CRP) impacts muscle wasting, while liver inflammation leads to insulin resistance and hepatic steatosis, aggravating the cachectic state." (PMID 39596015, 2024). "In the intervention group, comparison of initial biochemical parameter values with values after 1 month revealed increases in blood glucose, homeostasis model assessment-insulin resistance (HOMA-IR), cortisol, HDL, creatinine, and CRP." (PMID 35944239, 2024). "C-reactive protein (CRP), body mass index (BMI), visceral fat area (VFA), and insulin resistance (IR) were higher in the D2 group than in the D1 group in the original cohort (P < 0.05)." (PMID 38191965, 2024). "MAFLD+/MASLD- individuals have hepatic steatosis with concurrent liver disease or exhibit only two components of metabolic syndrome (insulin resistance assessed by HOMA and inflammation assessed by CRP levels)." (PMID 38926784, 2024).
Insulin resistance (continued). "Their data is suggestive of a chronic inflammatory state in women with PCOS, with BMI and insulin resistance being the main predicting factors of the increased WBC and CRP levels." (PMID 39610634, 2024). "Fasting venous blood sampling was performed to assess insulin resistance (HOMA-IR) and high-sensitivity-C-reactive protein (hsCRP)." (PMID 38577274, 2024). "The MetS severity score is significantly correlated with pathophysiological biomarkers of MetS, including the Homeostasis Model for Insulin Resistance (HOMA-IR), C-reactive protein (CRP), uric acid, and adiponectin." (PMID 38489287, 2024). "The findings of our study demonstrated that THC treatment reduces weight gain, fasting blood sugar (FBS), insulin resistance, testosterone levels, total cholesterol (TC), low-density lipoprotein (LDL) levels, and C-reactive protein (CRP) levels." (PMID 38911246, 2024). "In a prospective study, researchers investigated the effects of a 20-week aerobic exercise program on the BMI, homeostatic model assessment of insulin resistance (HOMA-IR), and high sensitivity-CRP (hs-CRP) levels of women with PCOS." (PMID 39610634, 2024). "For the PCOS versus control cohorts, age was matched, but PCOS subjects had a greater body mass index (BMI), showed increased insulin resistance (HOMA-IR), hyperandrogenemia, and increased CRP (as a marker of inflammation)." (PMID 38732117, 2024). "We also observed inverse correlations between several PCs and LPCs and fasting plasma glucose and insulin, as well as the homeostatic model assessment for insulin resistance (HOMA-IR) and inflammatory markers such as IL6 and C-reactive protein (CRP)." (PMID 39195560, 2024). "Female patients had lower glucose, insulin resistance (HOMA) index, and higher HDL and CRP concentrations than men." (PMID 36814510, 2023). "Markers of inflammation, such as serum C-reactive protein (CRP), interleukin (IL)-6 and tumor necrosis factor (TNF)-α, are, in fact, significantly elevated in patients with insulin resistance." (PMID 36675217, 2023). "It has been shown that C-reactive protein (CRP), a systemic acute phase protein, is a predictor of CVD at levels > 2 mg/l and a marker of insulin resistance." (PMID 37891561, 2023). "Insulin resistance (HOMA-IR) and hs-CRP were also measured, whilst QoL was measured using the SF-36 (short-form-36), self-administered, questionnaire." (PMID 36782338, 2023). "In the presence of insulin resistance, proinflammatory cytokines such as TNF-α, monocyte chemotactic protein-1 (MCP-1), C-reactive protein (CRP), and interleukins are increased." (PMID 36834911, 2023). "CRP during pregnancy and in the early postpartum predicted higher weight, body fat, VAT, higher prevalence of the MetS and increased insulin resistance (HOMA-IR, MATSUDA) at 1 year postpartum." (PMID 37891561, 2023). "Anthropometric indices, glycemia, insulin resistance, lipid profile, enzymes (ALT, AST, GGT, ALP), CRP, N-terminal propeptide of type I procollagen (P1NP) and collagen type I C-telopeptide (CTX-1) levels were measured." (PMID 37630857, 2023). "Interestingly, a study among participants of the NHANES survey showed that in women, extending the nighttime fasting duration was associated with lower levels of C-reactive protein level (but not with insulin resistance models) only among those who ate fewer than 30% of their calories after 5PM51." (PMID 38097547, 2023). "As expected, women with AN were much leaner, had lower fasting serum concentrations of glucose and insulin, higher insulin sensitivity as estimated by homoeostatic model assessment for insulin resistance (HOMA-IR) and lower serum C-reactive protein." (PMID 37069399, 2023). "Insulin-resistance biomarkers (HOMA), CRP, and oxidant–antioxidant status (MDA-Paraoxonase) were also measured." (PMID 37623840, 2023).
Insulin resistance (continued). "Several pro-inflammatory cytokines, such as the C-reactive protein (CRP), tumor necrosis factor-α (TNF-α) and interleukin-6 (IL-6), have been unequivocally shown to promote both insulin resistance (IR) and atherogenesis." (PMID 36900073, 2023). "Increased CT BoD, NLR, CRP, IL-6, PCT, insulin resistance indices, and hyperglycemia during hospitalization, as well as decreased PFR were associated with longer hospitalization." (PMID 37515156, 2023). "Blood analysis in one study examined homeostatic model assessment of insulin resistance (HOMA-IR) and highly sensitive CRP (Hs-CRP)." (PMID 37366934, 2023). "Serum homocysteine, insulin, homeostatic model assessment of insulin resistance (HOMA-IR), and hs-CRP were assayed." (PMID 36751256, 2023). "For the four proteins that differed between PCOS subjects and control women (ApoE, ApoM, C3, and HCFII), correlations with age; BMI; insulin resistance (HOMA-IR); testosterone; and circulating levels of TG, cholesterol, HDL-C, LDL-C, and CRP were performed." (PMID 36980195, 2023). "randomized sixty-nine patients with PD to a multi-strain probiotic or placebo, and after twelve weeks, patients taking the probiotic had lower inflammatory markers such as c reactive protein (CRP) and better metabolic profiles such as lower insulin resistance." (PMID 38292855, 2023). "Selected stress and age related biological outcomes were insulin resistance (HOMA-IR), systemic inflammation (IL-6, CRP), and cellular aging (leukocyte telomere length)." (PMID 34357581, 2022). "Systemic markers such as CRP, TNF-α, and IL-6 play an important role in both the progression of COPD and the development of insulin resistance." (PMID 35628022, 2022). "Higher DKK-1 levels were observed in patients with older age, a current smoking habit, lower insulin resistance reflected by the HOMA-IR index, lower HDL cholesterol, lower eGFR, higher triglycerides, higher platelet count, higher CRP, and higher NT-proBNP." (PMID 36291617, 2022). "Specifically, the median values of CRP and HOMA-IR in our MUH group were 0.07 and 2.47, respectively, which were close to the upper normal limits to define systemic inflammation and insulin resistance." (PMID 35417494, 2022). "In this review we propose that APPs, PAI-1, SAA, and CRP, could be the causative rather than only a correlative link between the physiological elements of risk (stress and inflammation) and the development of insulin resistance." (PMID 35883605, 2022). "Traditional CVD risk measures included blood pressure, central adiposity, lipids, insulin resistance (HOMA-IR), CRP and ASCVD score." (PMID 35271614, 2022). "The high levels of BMI, triacylglycerol and C-reactive protein, low level of HDL-cholesterol, and the markedly increased levels of sphingo- and glycerophospholipids also support the presence of severe insulin resistance." (PMID 35763031, 2022). "This study explored the correlation between plasma higher leptin levels, homeostasis model assessment of insulin resistance (HOMA-IR) index, hs-CRP and glycolipid metabolism in patients with chronic schizophrenia (CS)." (PMID 36090349, 2022). "GDM is a pro-inflammatory state as evidenced by raised C-reactive protein (CRP) levels; increased oxidative stress is found in GDM, secondary to insulin resistance, leading to lower CFH and higher C3 levels." (PMID 35628864, 2022). "Increasing levels of chronic subclinical inflammatory markers, such as C-reactive protein (CRP) and interleukin-6 (IL-6), are thought to be involved in the development of T2DM via insulin resistance onset and insulin secretion disruption." (PMID 35682821, 2022). "Subsequently, insulin resistance stemming from excessive caloric intake can stimulate proinflammatory mediators and cytokines such as TNF-α, IL-6 and CRP." (PMID 35252372, 2022).
Insulin resistance (continued). "Higher levels of IL-6, TNF-α, and C reactive protein (CRP) have been found in diabetic patients, and it is known that high CRP levels are correlated to insulin resistance due to impaired intracellular insulin signaling." (PMID 35996409, 2022). "Metadata types assessed included schizophrenia diagnosis, laboratory-measured hs-CRP level, age, body mass index (BMI), triglyceride measurement, HOMA-IR (an insulin resistance score), and cholesterol measurement." (PMID 34741130, 2022). "HDL-C, LDL-C, TC, TG, CRP, TNF-α, and IL-6 levels were abnormal in the HFD group, indicating harm to lipid metabolism and inflammation after a HFD-induced insulin resistance diet." (PMID 35907080, 2022). "Values of fasting serum insulin, C-reactive protein (CRP), and indicators of insulin resistance were higher in the affected individuals." (PMID 35206286, 2022). "In clinical trials, almond consumption has been related to reductions in insulin resistance, and serum levels of low-density lipoprotein (LDL), lipoprotein(a), and C-reactive protein (CRP) and other biomarkers of inflammation." (PMID 36698469, 2022). "In T2DM, as well as in insulin resistance, there is increased production of IL-6, IL-1β, IL-18, tumor necrosis factor (TNF-a), alpha-1 antichymotrypsin and C-reactive protein." (PMID 35453527, 2022). "Compared with baseline, BCSs experienced significant reductions in most of the metabolic and inflammatory parameters analyzed, including those related to insulin resistance (i.e., glycemia, insulin, and HOMA-IR) and inflammation (hs-CRP)." (PMID 34204528, 2021). "In the study group the insulin resistance index HOMA-IR and the CRP concentration were significantly higher if compared to the controls (p = 0.006 and p = 0.01, respectively)." (PMID 34441766, 2021). "In fact, obese patients with insulin resistance had systemic arterial dysfunction concurrent with high M1 ATMs and TNFα mRNA in SAT and elevated serum C reactive protein (CRP), indicating a proinflammatory state." (PMID 33897419, 2021). "Recent evidence suggests a positive relationship between inflammatory markers including IL-1β, IL-6, CRP and TNF-α and insulin resistance." (PMID 34078385, 2021). "There were also positive correlations between LCN2 and parameters of insulin resistance: fasting plasma glucose (FGP), HOMA-IR, fasting plasma insulin (FPI), high-sensitivity C-reactive protein (hs-CRP), total cholesterol, and triglyceride." (PMID 34212049, 2021). "In the present study, AGM intake reduced the serum activities of γ-GT and ALT and serum CRP concentrations, which suggests AGM can reduce hepatic insulin resistance and inflammation." (PMID 34359426, 2021). "Of note, a cross-sectional study including 40 prediabetic and 40 control subjects gave evidence for a positive correlation of sRANKL with prediabetes, BMI, insulin resistance (HOMA-IR) and also markers of inflammation (hs-CRP)." (PMID 35054232, 2021). "High-sensitivity C-reactive protein (hs-CRP), fasting blood glucose (FBG) and insulin concentrations, and homeostatic model assessment for insulin resistance (HOMA-IR) were assessed at baseline, as well as end of weeks two and three." (PMID 34405148, 2021). "Maternal fasting glucose, insulin, homeostatic model assessment of insulin resistance (HOMA-IR), leptin, TNF-alpha, C-reactive protein, adiponectin, and lipids are measured by trained staff at each research site, following the established protocols." (PMID 33827659, 2021). "It should be noted that the nutritional modification carried out was effective in relation to other parameters: a decrease in CRP, HOMA-IR (Homeostasis Model Assessment of Insulin Resistance), or HbA1c (Glycated Haemoglobin)." (PMID 34836342, 2021). "Several parameters including blood glucose, lipid profile, CRP, TNF-α, IL-10, and insulin resistance (IR) were measured over the whole study period." (PMID 35096939, 2021).